ADM5 (adrenomedullin 5 (putative))
Description:
Probable non-functional remnant of adrenomedullin-5.
Synonyms: C19orf76; AM5
Tractability: Antibody: UniProt places it where antibodies can reach, with high confidence; UniProt predicts a signal peptide or a membrane-spanning region; its Gene Ontology location is reachable by antibodies, with medium confidence.
Gene: Protein-coding gene on chromosome 19 (49,688,953 to 49,690,575, forward strand). Ensembl gene ENSG00000224420.
Subcellular location: Secreted
Gene Ontology:
Molecular function: hormone activity
Biological process: adenylate cyclase-activating G protein-coupled receptor signaling pathway; adrenomedullin receptor signaling pathway; positive regulation of heart rate; regulation of systemic arterial blood pressure; regulation of urine volume
Cellular component: extracellular region
Genetic constraint (gnomAD): Loss-of-function variants: 1 observed, 1.61 expected, observed/expected ratio (o/e) 0.62, 90% interval 0.2 to 1.82. That is too few expected variants to judge how well the gene tolerates losing a copy. Missense variants: 192 observed, 193.86 expected, observed/expected ratio (o/e) 0.99, 90% interval 0.88 to 1.12. Synonymous variants: 90 observed, 86.19 expected, observed/expected ratio (o/e) 1.04, 90% interval 0.88 to 1.24.
Homologues: Orthologues: macaque ADM5 (82% identical), dog ADM5 (59% identical).
Diseases named in the same sentence as ADM5 in open-access papers:
ADM5 is named in the same sentence as 4 diseases in open-access papers, as found by Europe PMC text mining. Sharing a sentence is not in itself a finding about the gene and the disease. The quoted sentences say what the papers report.
breast carcinoma (1 paper, 2026). "High expression of ADM5 was associated with poor breast cancer patient survival in the basal PAM50 cancer subtype compared to normal and luminal subtypes." (PMID 41776551, 2026).
cancer (1 paper, 2026). A tumor composed of atypical neoplastic, often pleomorphic cells that invade other tissues. "Further, across multiple cancer types, high ADM5 expression was associated with reduced patient survival in anti-PD1- and anti-CTLA4-treated patients but not in anti-PDL1-treated patients." (PMID 41776551, 2026). "CLEC14a and EMCN were validated as TEC markers, extending their annotation in breast TEC, and ADM5 identified as a novel TEC marker in breast and other cancers." (PMID 41776551, 2026). "Moreover, as ADM5 is associated with reduced patient overall survival, this data suggests that a better understanding of ADM5 and other TEC-specific response pathways may provide novel approaches to reactivate anergic TECs and lead to effective therapeutic interventions for cancer patients." (PMID 41776551, 2026).
tumor (1 paper, 2026). "ADM5, a novel tumor vascular marker, was enhanced in TEC venules and less so in arteriole or capillaries." (PMID 41776551, 2026). "CLEC14a, EMCN, and ADM5 were further validated in the single-cell Curated Cancer Cell Atlas (3CA) to be highly specific to the endothelial cell clusters across multiple tumor types, while IGFBP4 was diversely expressed in endothelial, fibroblast, and some malignant cell types." (PMID 41776551, 2026).
ADM5 also shares sentences with these, for which no sentence is quoted: staphylococcus aureus infection (1 paper).